GATA3 (GATA binding protein 3)
Diseases named in the same sentence as GATA3 in open-access papers (continued):
Sharing a sentence is not in itself a finding about the gene and the disease.
breast tumors (continued). "The high frequency of GATA3 mutations in breast tumours is thus not well represented in cell lines." (PMID 27588951, 2016). "Flow cytometry analysis of PyMt cell line-derived breast tumors and tumor-draining lymph nodes from Tslptg and WT mice revealed increased CD4+ T cells, especially GATA3+ CD4+ T cells in Tslptg compared with WT mice." (PMID 36467403, 2022). "In our cases, cytokeratin 7, TTF-1, p63, and p40 for lung tumors; CK7, GATA3, and GCDFP-15 for breast tumors; and cytokeratins, synaptophysin, chromogranin, and CD56 for neuroendocrine tumors were the most used markers." (PMID 35308701, 2022). "The transferred CD4+ T cells became highly proliferating GATA3+ CD4+ T cells in the tumor-draining lymph nodes and breast tumors of Tslp-PyMttg Rag1KO mice." (PMID 35657353, 2022). "A stronger correlation was observed between GATA3 and TBX3 expression in normal breasts as compared with the breast tumor samples." (PMID 31910858, 2020). "Of the 35 upregulated genes, 5 were all related to breast tumor types: CASP8 (0.7-fold upregulation), CDH1 (1.21-fold upregulation), GATA3 (3-fold upregulation), ESR1 (3-fold upregulation) and FOXA1 (+ 2.89-fold upregulation)." (PMID 31182966, 2019). "The expression levels of GATA3 and ESR1, which are both the breast tumor-related genes, showed upregulation in tumor tissues compared with normal tissues." (PMID 31182966, 2019). "Immunohistochemical ERα, GATA3, and FOXA1 expression levels vary between primary breast tumors and paired metastases." (PMID 29972720, 2018). "GATA3 is thought to play a key role in making enhancer elements accessible to ER-α and its expression is highly correlated with both ER-α and FOXA1 in breast tumours." (PMID 25652398, 2015). "GATA3 and FOXA1 are correlated with ERα positive breast tumors and are critical in normal mammary gland development in rodent models." (PMID 24339902, 2013). "According to literature report, Mamglb, GATA binding protein 3 (GATA-3) and gross cystic disease fluid protein 15 (GCDFP-15) are less effective on proving the origin of salivary gland-type breast tumor, while SOX-10 may be more effective." (PMID 41040523, 2025). "In addition to known TFs such as GATA3 and FOXP1, we identify HNF1A as a TF specific to luminal A/B breast tumors and LM breast duct cells." (PMID 39478117, 2024). "Our two‐gene (GATA3 and AGR3) IHC‐based panel could classify the histologic grade III ER+HER2− breast tumors into luminal‐like and non‐luminal‐like subtypes, for whom the benefit from endocrine therapy is limited." (PMID 34146382, 2022). "HER2-low breast tumors had significantly more frequent mutations in phosphatase and tensin homolog (PTEN; p < 0.001), GATA binding protein 3 (GATA3; p < 0.001), core-binding factor subunit beta (CBFB; p < 0.001), and AKT serine/threonine kinase 1 (AKT1; p < 0.001) than HER2-positive breast tumors." (PMID 35484593, 2022). "Although GATA-3 has been reported to be highly sensitive for breast tumors, it is not entirely specific." (PMID 29116378, 2018). "For example, protein levels of CCNB1 (cyclin B1) were significantly higher (P = 7.28E‐13) in breast tumors with alterations in FAM83 family genes, whereas protein levels of GATA3 (P = 3.79E‐07), PGR (P = 5.77E‐07), and ESR1 (P = 9.20E‐07) were significantly lower." (PMID 28078827, 2017). "We further characterized several transcription factors linked to a large number of enhancers in each tumor type, including GATA3 in non-basal breast tumors, HOXC6 and DLX1 in prostate tumors, and ZNF395 in kidney tumors." (PMID 27833659, 2016). "The PR gene, PGR, and 3 other genes (GATA3, STC2 and GLI3) are increased in their expression, whereas the expression of 6 genes (AURKA, BUB1, CDC20, MKI67, HJURP, and CENPA) is decreased in PR-positive breast tumors." (PMID 22022496, 2011).
breast tumors (continued). "Here we report the characterization of human breast tumors of both genders for cistromic make-up of hormonal regulation in human tumors, revealing genome-wide chromatin binding landscapes of ERα, AR, PR, GR, FOXA1, and GATA3 and enhancer-enriched histone mark H3K4me1." (PMID 29396493, 2018). "Importantly, this probe was specifically unmethylated in non-basal breast tumors, likely due to the higher expression of GATA3 in luminal, as compared to basal tumors." (PMID 27833659, 2016). "In addition, basal breast tumors are characterized by low ER and PR expression as well as high levels of EGFR, elevated expression of AKT3, CD44 and MET and decreased GATA3 expression; features that are also consistent with each of the HER2 related subgroups investigated in the current study." (PMID 21672245, 2011).
urothelial carcinoma (82 papers, 2012 to 2026). A malignant neoplasm derived from the transitional epithelium of the urinary tract (urinary bladder, ureter, urethra, or renal pelvis). "Our data do not support a major regulatory role of GATA3 copy number gains for GATA3 expression in urothelial carcinoma although there was a significant statistical association between GATA3 gene copy number and expression." (PMID 39979991, 2025). "In this study, we investigated the clinical and biological significance of GATA3 polymorphisms and protein expression in urothelial carcinoma (UC) through an integrative approach combining SNP genotyping and immunohistochemistry." (PMID 40650155, 2025). "The immunohistochemical (IHC) profile showed positivity for cytokeratin (CK) and carcinoembryonic antigen (CEA), with negativity for markers typically associated with RCC (e.g., PAX8, CD10) and urothelial carcinoma (e.g., GATA3, uroplakin)." (PMID 40351999, 2025). "GATA3 is a transcription factor involved in urothelial differentiation and is widely used as a diagnostic marker for urothelial carcinoma (UC)." (PMID 40650155, 2025). "GATA3 is a plausible diagnostic biomarker for urothelial carcinoma as it enables differentiation from other genitourinary malignancies." (PMID 39768217, 2024). "This study aimed to evaluate the diagnostic and prognostic roles of GATA-binding protein 3 (GATA3) immunohistochemistry in urothelial carcinoma (UC) using a meta-analysis." (PMID 37629741, 2023). "GATA-Binding Protein 3 (GATA3) is a zinc finger transcription factor that has been used in human medicine as a diagnostic and prognostic marker of urothelial carcinoma." (PMID 35324835, 2022). "For example, loss of GATA3 was associated with tumor progression and poor patient outcomes in BC and urothelial carcinoma." (PMID 35016723, 2022). "GATA3 staining cannot distinguish intraepithelial PD from pagetoid squamous cell carcinoma in situ or primary EMPD from secondary EMPD caused by urothelial carcinoma." (PMID 28693610, 2017). "GATA3 is a very sensitive and specific marker for urothelial carcinomas and their variants." (PMID 37924117, 2023). "CCACLUT has consistent GATA3 expression, which may cause challenge in the diagnosis of urothelial carcinoma but can be used to distinguish CCACLUT from CCACFGT." (PMID 36320040, 2022). "GATA3 is a transcription factor expressed in breast and urothelial epithelial cells, and its positivity is a sensitive and specific marker for urothelial carcinoma." (PMID 40656261, 2025). "GATA3 is also expressed in urothelial carcinoma, skin adnexal tumors, paraganglioma, T-cell hematopoietic malignancies, among others." (PMID 40025593, 2025). "GATA3 positivity in urothelial carcinoma limits its usage when the differential diagnosis is bladder cancer." (PMID 40025593, 2025). "GATA3 and 34βE12 are relatively specific immunohistochemical markers for urothelial carcinoma, which played a crucial role in differentiation." (PMID 40917856, 2025). "We evaluated the expression of basal markers (cytokeratin (Ck) 5, p63), luminal markers (Ck8, Ck20), a tumor initiating marker (CD44), a proliferating marker (Ki67), and urothelial carcinoma markers (GATA3, uroplakin II (UPKII)." (PMID 39921252, 2025). "In a large series of 32 patients with the plasmacytoid subtype, a significantly lower level of basal markers CK5/6 and p63 was demonstrated compared to conventional urothelial carcinoma, alongside high expression of luminal markers GATA3 and CK20." (PMID 41003151, 2025). "GATA3 staining is sensitive for breast and urothelial carcinoma, however, a study showed it is also sensitive for cutaneous epithelial neoplasms." (PMID 40225096, 2025). "Mesotheliomas can exhibit the GATA-3 antibody, which is also present in breast and urothelial carcinomas." (PMID 39407894, 2024). "GATA-3 is a urothelial marker that can differentiate urothelial carcinoma from prostatic adenocarcinoma." (PMID 38142529, 2024).
urothelial carcinoma (continued). "In summary, the results of our study demonstrate that Upk1a and/or Upk1b IHC can well complement GATA3 for the distinction of urothelial carcinomas." (PMID 37777995, 2024). "In summary, the results of our study demonstrate that Upk1a and/or Upk1b immunohistochemistry can complement GATA3 for the distinction of urothelial carcinomas." (PMID 37777995, 2024). "Recently, an antibody against the transcription factor GATA3 has been developed, that presents lower specificity for urothelial carcinoma but remains useful for identifying poorly differentiated tumors." (PMID 39336523, 2024). "GATA3, a member of the GATA family of zinc finger transcription factors, has emerged as a valuable diagnostic marker in urothelial carcinoma." (PMID 38425344, 2024). "For comparison with established markers for the distinction between urothelial carcinomas and renal cell carcinomas, we also performed sensitivity and specificity calculation of p63 and GATA3." (PMID 39105782, 2024). "In our case, pathological findings showed luminal-type urothelial carcinoma with GATA3, CK20, and uroplakin-positive." (PMID 38882557, 2024). "High expression of NECTIN4 or GATA3 in de novo NEPC regions is characteristic of urothelial carcinoma." (PMID 37240308, 2023). "Counterintuitively, few studies have investigated GATA3 as a regulator of PPARγ expression in the context of urothelial carcinoma." (PMID 37250326, 2023). "In summary, this study highlights GATA3's potential in distinguishing urogenital malignancies, particularly high-grade urothelial carcinoma, from poorly differentiated prostate cancer." (PMID 38161907, 2023). "We also found that MGP was positive in only 2 of 218 cases (0.9%) of urothelial carcinoma, which is known to be frequently labeled with GATA3 (70–90%,)." (PMID 36284362, 2022). "GATA3 expression is vastly utilized in the breast and the urothelial carcinomas due to its high specificity; and many other benign and malignant lesions arising from skin, kidney, uterus, testis, ovary, and pancreas." (PMID 36320040, 2022). "GATA3 can also be considered a sensitive and specific marker for urothelial carcinoma and as a criterion for BLCA subtypes classification." (PMID 35647011, 2022). "GATA3 positivity is a finding which ought to be taken into consideration should urothelial carcinoma, which is typically also GATA3-positive, enter the differential diagnosis." (PMID 35327459, 2022). "Since then, GATA3 has been deemed a useful marker for detecting primary and metastatic urothelial carcinomas." (PMID 33803938, 2021). "Closer examination, however, demonstrated that GATA3 expression was more frequently detected in low-grade urothelial carcinomas than in high-grade cases." (PMID 33803938, 2021). "GATA binding protein 3 (GATA3), member of a zinc finger transcription factor family, is crucial for the differentiation of many tissues and a very sensitive marker for breast and urothelial carcinomas." (PMID 33504059, 2021). "GATA3 was widely expressed in bladder tumours, especially urothelial carcinomas, with higher expression of GATA3 in low grade and low stage tumours." (PMID 34690921, 2021). "It has been demonstrated that NECs of the urinary bladder are consistently p16-positive, CK20-negative, GATA3-negative, and p63-negative, whereas high grade urothelial carcinomas show an opposite profile (p16-, p63+, GATA3+, and CK20+)." (PMID 33169199, 2021). "It was reported that GATA3 was expressed in most urothelial carcinomas, consistent with its physiological expression profiles and biological roles in the urinary tract." (PMID 33803938, 2021). "We additionally highlight the utility of GATA-3 immunostaining in identifying urothelial carcinoma histologically." (PMID 30349834, 2018). "GATA3 is a marker of urothelial differentiation, expressed in 70% to 90% of urothelial carcinomas but is often lost in primary bladder adenocarcinomas, with the exception of signet-ring cell carcinoma of the urinary bladder." (PMID 29621151, 2018).
urothelial carcinoma (continued). "Whereas GATA3 expression remained mostly negative in prostate and renal cell carcinoma, up to 70% of invasive urothelial carcinomas were GATA3 positive in one study." (PMID 28005163, 2017). "Immunopositivity for GATA3 is maintained in poorly differentiated urothelial carcinoma; uroplakin II is expressed in approximately 60% high-grade urothelial carcinoma." (PMID 27642214, 2016). "Decrease in E-cadherin expression is noted in poorly differentiated urothelial carcinoma, and a loss of expression is a feature of the plasmacytoid variant of urothelial carcinoma, which is similar to ILC and expresses GATA3." (PMID 27642214, 2016). "Since it resembled a poorly differentiated urothelial carcinoma, immunohistochemistry was performed with markers positive for urothelial carcinoma, such as uroplakin II, GATA3, p63, p40, and 34βE12." (PMID 27642214, 2016). "Considering the viewpoint of differential diagnosis, the distinction between IPLC and poorly differentiated urothelial carcinoma seems to be difficult when encountering GATA3-expressing poorly differentiated metastatic carcinoma." (PMID 27642214, 2016). "Supraclavicular node biopsy supported the diagnosis of stage IV urothelial carcinoma with GATA3 positive, cytokeratin 7 (CK 7) positive, and cytokeratin 20 (CK 20) negative immunohistochemistry." (PMID 26634162, 2015). "Differentiating mucinous adenocarcinomas from other carcinoma subtypes using immunohistochemistry (IHC) is difficult, as the markers CK7 and GATA3 are commonly expressed in other types of urothelial carcinomas." (PMID 26630940, 2015). "GATA3 is the most commonly used IHC marker for the identification of urothelial carcinomas." (PMID 37777995, 2024). "One of the main diagnostic challenges with GATA3 is its expression in other non-breast malignancies, including urothelial carcinomas, parathyroid tumors, and certain gynecological malignancies." (PMID 39518009, 2024). "Thus, GATA3 represents an attractive sensitive and specific marker for detection, staging, and therapeutic management in urothelial carcinoma." (PMID 39768217, 2024). "ALES may overlap the morphology of nested urothelial carcinoma, but urothelial markers such as GATA3, UroII, CK7, CK20 cannot be detected in current case." (PMID 37518334, 2023). "GATA3 belongs to the family of transcription factors that recognizes G-A-T-A nucleotide sequences in the target gene and is mostly used as a marker for breast and urothelial carcinomas." (PMID 36816543, 2023). "GATA3's strong positivity in high-grade urothelial carcinoma cases is promising for diagnostics." (PMID 38161907, 2023). "Along with morphologic clues, immunohistochemical panel of PAX8, GATA3, and p63 might be useful to distinguish these tumors from urothelial carcinoma." (PMID 36320040, 2022). "However, GATA3 is also expressed in normal urothelial epithelia and in 80% to 90% of urothelial carcinomas." (PMID 29621151, 2018). "Over-expression of GATA3 protein was observed in 67% of urothelial carcinomas." (PMID 23284679, 2012). "Notably, markers typically associated with RCC (PAX8, CD10) and urothelial carcinoma (GATA3, uroplakin) were negative, supporting a diagnosis of primary adenocarcinoma." (PMID 40351999, 2025). "Besides, GATA3 was also downregulated in prostate, urothelial carcinoma." (PMID 27893417, 2017). "The luminal marker GATA3, urothelial marker CK20, urothelial carcinoma marker UPK2, and squamous epithelium marker p40 were identified, indicating that the PDO of human bladder cancer was successfully constructed." (PMID 39651805, 2025). "The positive results of GATA3 and UPKII staining confirmed that our PDOs originated from urothelial carcinoma." (PMID 39921252, 2025). "GATA binding protein 3 (GATA3) belongs to the GATA transcription factor family and is found exclusively in breast and urothelial carcinomas." (PMID 40636692, 2025).